CD47 (CD47 molecule)
Diseases named in the same sentence as CD47 in open-access papers (continued):
Sharing a sentence is not in itself a finding about the gene and the disease.
leukemia (continued). "In summary, we demonstrated that SIRPα-αCD123 antibodies specifically target LSCs, mediate their efficient clearance and stimulate phagocytosis of AML while restricting CD47-related on-target off-leukaemia toxicity." (PMID 34579739, 2021). "Overexpression of CD47 enables cancer cells to escape immune surveillance and destruction by phagocytes both in solid tumours and leukaemia." (PMID 33449453, 2021). "These early results suggest that perhaps different classes of anti-CD47 therapeutic drugs, or combinations with other types of anti-leukemia therapies, should be explored in future AML studies." (PMID 32677994, 2020). "Increasing evidences have shown that CD47 expression was elevated in tumor cancer tissues and cells, such as bladder cancer, leukemia, colon cancer and NSCLC." (PMID 32314789, 2020). "Under inflammatory conditions and during cytokine mobilization, the expression of CD47 in normal hematopoietic stem cells is upregulated, and leukemia progenitor cells use this mechanism to evade macrophage-mediated phagocytosis." (PMID 32082311, 2020). "Such interactions can also facilitate immune evasion, as exemplified by upregulation of CD47 on leukemia cells that inhibit phagocytes by binding to SIRP-α." (PMID 32460032, 2020). "CD47 blockade using an antibody that is specific for an extracellular domain of CD47 augmented apoptosis of leukemia and myeloma cells." (PMID 32082311, 2020). "Through direct competition with SIRPα on the surface of macrophages, E. coli-constructed recombinant hSIRPext binds to CD47 on the surface of leukemia stem cells, which blocks CD47-SIRPα signaling." (PMID 32082311, 2020). "In this study, we observed that SIRPα overexpression in BMDMs decreased phagocytosis of L1210 leukemia cells, while SIRPα knockdown in BMDMs and CD47 knockdown in L1210 cells both increased phagocytosis by macrophages." (PMID 30105024, 2018). "While all IgG2σ anti-CD47 mAbs suppressed leukemia growth similar to IgG1 anti-CD47 mAbs in the Kasumi-3 model, anti-leukemic effects of the IgG2σ anti-CD47 mAbs were less pronounced in the HL60 and MV4-11 models." (PMID 28234345, 2017). "During viral packaging, the sCAR-ligand fusion protein would be expressed in packaging cells and non-covalently installed on viral surface, bridging oncolytic adenoviruses to CD123+ or CD47+ leukemia cells." (PMID 28335432, 2017). "The antibody, named ZF1, can block the interaction of CD47 and SIRPα, enhancing phagocytosis of leukemia cells by macrophages." (PMID 27863402, 2016). "Recently, CD47 was reported to be a marker of tumor-initiating cells in leukemia and bladder cancer." (PMID 26093091, 2015). "We previously demonstrated that blocking monoclonal antibodies against human CD47 enable the phagocytic elimination of leukemia cells and cancer cells from many human solid tumors." (PMID 26390038, 2015). "All human cancers studied to date, including both solid tumors and leukemia, express CD47, making CD47 a universal target in human cancer." (PMID 26390038, 2015). "In this study, we demonstrated that Hu5F9-G4 blocks the CD47-SIRPα interaction and potently enables the phagocytosis of leukemia cells." (PMID 26390038, 2015). "As a consequence, leukemia cells expressing high levels of CD47 are likely selected to counter pro-phagocytic signals." (PMID 26390038, 2015). "From this model, we predicted that blockade of the CD47-SIRPα interaction would result in dominance of pro-phagocytic signals resulting in phagocytosis of the leukemia cells." (PMID 26390038, 2015). "CD47 is a critical regulator of phagocytosis that is expressed on leukemia and cancer cells where it functions to inhibit phagocytosis by cells of the innate immune system." (PMID 26390038, 2015). "In this way, leukemia cells are dependent on CD47 expression to prevent phagocytic elimination by innate immune cells." (PMID 26390038, 2015).
leukemia (continued). "Paired receptors are an increasingly important group of targets as indicated by CD200/CD200R in leukemia and CD47/SIRP in many cancers." (PMID 23691022, 2013). "Therapeutic antibodies targeting CD47 interrupted the CD47-SIRPα interaction and enabled phagocytosis of leukemia stem cells by macrophages." (PMID 24019967, 2013). "CD47 upregulation was recently found to serve as a mechanism for leukemia stem cells/progenitors to avoid phagocytosis." (PMID 24073274, 2013). "Previously, CD47 on leukemia stem cells was shown to interact with macrophage signal regulatory protein α (SIRPα) and avoid phagocytosis through inducing a “do not eat” signal." (PMID 24019967, 2013). "Moreover, TAMs can induce increased CD47 expression on various CSCs, such as leukemia, HCC, and pancreatic cancer." (PMID 40647402, 2025). "Other studies implicated MYC, a well-characterized TF with strong oncogenic potential, in the transcriptional regulation of CD47 during the progression of leukemia using MYC-induced T cell acute lymphoblastic leukemia mouse model; MYC T-ALL, and human leukemia cells lines; CCRF-CEM and Jurkat." (PMID 39742254, 2024). "Notably, leukemia cells circulate naturally in the blood and will be destroyed by macrophages in the spleen upon administration of the CD47 blockade treatment." (PMID 38920727, 2024). "Moreover, therapeutic blockade of the CD47/SIRPα axis using anti-CD47 mAbs has demonstrated efficacy in a variety of preclinical models and is currently in clinical trials for both leukemia and solid tumors." (PMID 36413402, 2023). "The surviving AML blasts uniquely rewired their profiles, characterized by increased activity of AKT and mTOR pathways, upregulation of YTHDF2, a transcription factor regulating RNA metabolism and counteracting apoptosis of leukemia cells, and increased expression of CD47 and HLA-ABC." (PMID 37386016, 2023). "Thus the selectivity of CD47 antibodies relies on the balance of CD47 as well as prophagocytic signals on normal cells and leukemia cells." (PMID 36497385, 2022). "Interestingly, IL-4 has two completely opposite effects in regulating mouse phagocytosis, it enhances macrophage-mediated killing of leukemia cells, but also induces CD47 expression, protecting target cells from excessive phagocytosis." (PMID 35721208, 2022). "Thus, blockade of CD47 has been shown to be an effective strategy for targeting leukemia CSCs in PDX models." (PMID 35046949, 2021). "In addition, CD47, was not only considered as TSCs-related gene in leukemia and bladder tumor, but also an important marker to evade phagocytosis." (PMID 34828292, 2021). "Moreover, blockage of CD47 with monoclonal antibodies enabled macrophage phagocytosis of AML leukemia stem cells and inhibited their tumorigenesis in vivo." (PMID 32314789, 2020). "Given the broad mechanism of action of CD47 targeting agents as macrophage checkpoint inhibitors and potential leukemia stem cell targeting, this raises the question of whether additional combinations incorporating anti-CD47 agents will be effective." (PMID 32038992, 2019). "However, forced overexpression of CD47 in MOLM13 cells led to dissemination of fulminant leukemia in vivo due to evasion of macrophage phagocytosis." (PMID 32038992, 2019). "Available evidence proves that CD47 help leukemia cells to avoid phagocytosis." (PMID 30285885, 2018). "Notably, CD47 was described as a marker of tumor-initiating cells in leukemia as well as in bladder and liver cancer." (PMID 26578962, 2015). "The CD200/CD200R interaction has similarities with the CD47 interaction with the SIRP paired receptor family in that both ligands are widely distributed but receptors are restricted mainly to myeloid cells and both CD200 and CD47 are targets for leukemia therapy." (PMID 23602662, 2013). "The histiocytic sarcomas and leukemias reported here uniformly express high levels of CD47." (PMID 22952867, 2012).
leukemia (continued). "Thus, CD47 expression on leukemia cells and SIRPα expression on LAMs were investigated." (PMID 40881683, 2025). "CD47, also known as integrin-associated protein (IAP), is an immunoglobulin-like protein extensively expressed on cell membranes, encompassing both normal cells and various types of tumor cells, including leukemia, lymphoma, and a diverse array of solid tumors." (PMID 38273373, 2024). "Furthermore, ovarian and triple‐negative breast cancers that were particularly susceptible to CD24 blocking did not respond well to CD47‐blocking therapy, and vice versa in leukaemia." (PMID 33449453, 2021). "Therefore, our results demonstrated that CD47-retargeted oncolytic adenoviruses armed with IL-24 could be valuable for the treatment of CD47+ leukemia." (PMID 26554307, 2015). "SIRPα-αCD123 fusion antibodies disrupted CD47/SIRPα signalling in AML cell lines and specifically enhanced leukemia stem cell clearance." (PMID 39697225, 2024). "Multiple groups established monoclonal antibodies against CD47 that enabled phagocytosis of AML leukemic stem cells in vitro and inhibited their growth in leukemia cell lines and mice models." (PMID 36497385, 2022). "Majeti and colleagues initially showed that blockade of the CD47-SIRPα axis using a monoclonal CD47 antibody can induce macrophage-mediated LSC killing and suppress in vivo leukemia development in experimental models." (PMID 33322769, 2020). "NI-1701, a BsAb that targets CD47 and CD19 was designed for B-cell lymphoma and refractory leukemia." (PMID 32677994, 2020). "To date, drugs targeting CD47, CD44 and c-met have been developed to treat breast, lung, colon and gastric cancer and leukemia." (PMID 25658794, 2015). "Several studies have showed that the aberrant expression of specific markers on the cell surface of leukemia progenitors is characteristic for LIC, differentiating them from their normal counterparts, including CD90, CD123, CLL-1, CD96, CD47, Tim3 and so on." (PMID 24517186, 2013). "Thus, we can see that our LSC, P11, showed to be beneficial as a model for CD47 and CD93 therapeutic research, while additional leukemia lines are needed to represent the pleura of AML subtypes fully." (PMID 36765677, 2023). "Apart from Cxcr4, the screen also identified Cd47 and Cd244 (also referred to as 2B4) as positive regulators of MLL-AF9 leukemia cells in vivo; both are known to play a role in immune regulation in normal hematopoiesis and to promote AML cell growth and survival." (PMID 32460032, 2020). "While the humanized anti-CD47 antibody (Hu5F9-G4) used in this study has been shown to block the CD47-SIRPα interaction and induce phagocytosis of leukemia cells we can not rule out the possibility of Fc mediated opsonization as human macrophages express high affinity Fc receptor FcRγ1." (PMID 27092773, 2016). "Additionally, studies using lentiviral vectors to deliver CD47‐siRNA into AML‐derived LSCs demonstrated effective inhibition of LSC proliferation and promotion of apoptosis, highlighting CD47 as a valuable target for leukemia treatment and prognostic prediction." (PMID 39445003, 2024). "Furthermore, a combination of miR-708 and anti-CD47 antibody treatment increases the phagocytic activity of macrophages against leukemic CEM cells compared with either agent alone, and could therefore be used as a combinatorial anti-leukemia therapy in future studies." (PMID 32082311, 2020).
lung cancer (73 papers, 2016 to 2026). A malignant neoplasm involving the lung. "Our findings illuminate an innovative strategy to enhance the efficacy of targeted therapies for lung cancers with oncogenic driver mutations by combining them with anti-CD47 agents." (PMID 38483480, 2024). "In lung cancer, CD47 expression is associated with poor survival and tumors with EGFR mutations, which do not typically respond to PD-1 blockade." (PMID 37958404, 2023). "In the future, when surgical specimens of lung cancer are obtained, we hope to investigate the association between CD47 SNP rs3804639 and CD47 protein expression by staining for the CD47 protein in tumors and surrounding immune cells." (PMID 37545625, 2023). "To further reveal CD47 roles in H2-mediated repression of lung cancer progression, we carried out the gain/loss-of-function assays." (PMID 32314789, 2020). "Then, we performed the loss-of-function assay to explore the role of CD47 in H2-mediated lung cancer repression." (PMID 32314789, 2020). "To investigate the therapeutic potential of combining EGFR inhibitors with anti-CD47 antibodies, we first examined whether CD47 could be a genuine target for lung cancers bearing driver mutations." (PMID 38483480, 2024). "Our findings have immediate translational implications since they suggest the combination of targeted therapies and CD47-blocking therapies could be an optimal strategy for treating patients with lung cancers with driver mutations." (PMID 38483480, 2024). "Further, we hypothesized that the CD47 SNPs reported in other cancers might be associated with lung cancer." (PMID 37545625, 2023). "Our findings are corroborated by recently demonstrated induction of macrophage phagocytosis of lung cancer cells and lung CSCs, as well as the inhibition of lung CSCs-induced tumor growth in immune-deficient mice xenograft models by blocking CD47 function with anti-CD47 antibodies." (PMID 31861233, 2019). "Moreover, H2 administration could significantly alleviate the pathological change of lung cancer tissues from the in vivo mice, as well as cause obvious decreases in CD47 and CDC42 expressions." (PMID 32314789, 2020). "Our study demonstrates that metformin treatment substantially decreases both CD47 protein and mRNA levels in lung cancer cells." (PMID 41539566, 2026). "Our data revealed that RASON knockdown downregulates CD47 expression, a key “don’t-eat-me” signal that inhibits macrophage-mediated phagocytosis of lung cancer cells." (PMID 40128846, 2025). "Taken together, these results indicate that RASON upregulates KRAS signaling and suppresses macrophage infiltration via upregulation of CD47, thereby promoting lung cancer progression and facilitating innate immune evasion." (PMID 40128846, 2025). "In agreement with this, blockade of autophagy using CQ or ATG7 gene knockout lung cancer cells led to increased CD47 protein levels." (PMID 39665172, 2025). "In summary, our study revealed that CGs significantly enhanced the anti‐lung cancer effect of CD47 antibody." (PMID 40985476, 2025). "This study unraveled that ouabain and digoxin significantly increased the phagocytic activity of macrophages and the efficacy of the CD47 antibody in lung cancer elimination in both in vitro and in vivo models." (PMID 40985476, 2025). "Our study provides the first evidence that the co‐administration of CD47 antibody and CGs has a significant anti‐cancer effect on lung cancer models." (PMID 40985476, 2025). "Here, we developed an unbiased, high-throughput screening platform to identify drugs that render lung cancer cells more vulnerable to macrophage attack, and we found that therapeutic synergy exists between genotype-directed therapies and anti-CD47 antibodies." (PMID 38483480, 2024). "In contrast, both CD47 expression and MHC class I expression was significantly lower in lung cancers with KRAS driver mutations." (PMID 38483480, 2024).
lung cancer (continued). "There exist multiple FDA-approved targeted therapies for lung cancer, and multiple CD47-blocking therapies are now under investigation in clinical trials." (PMID 38483480, 2024). "We previously observed that SIRPG-expressing lung cancer cells displayed stemness properties and transmitted the immune escape signal through sustaining CD47 expression." (PMID 38833156, 2024). "We also examined CD47 expression on primary lung cancer cells from malignant pleural effusions and observed high CD47 expression on the cell surface." (PMID 38483480, 2024). "Through ceRNA with miR-519d-5p, KCTD21-AS1 treatment suppressed the numbers of phagocytosis of macrophages compared with the control, indicating that KCTD21-AS1 promoted the tumorigenesis of lung cancer via miR-519d-5p-blocking CD47." (PMID 38383737, 2024). "Together, these findings indicate that our in vitro findings translate to in vivo models and that dual blockade of CD47 and oncogenic drivers can enhance antitumor responses to lung cancer." (PMID 38483480, 2024). "For example, it has been reported that blocking CD47 in lung cancer activates macrophage-mediated phagocytosis and enhances the anti-tumor effect." (PMID 37545625, 2023). "CD47 is an immune suppressor protein that is known to be up-regulated in lung cancer cells exposed to nicotine." (PMID 37888026, 2023). "In 3 independent cohorts of patients with lung cancer, the KRAS mutation status positively correlated with CD47 expression." (PMID 36413402, 2023). "Here the authors report the design of a pH-responsive nanomedicine for the co-delivery of a T-type calcium channel inhibitor and of a small molecule targeting CD47, promoting anti-tumor immune responses in orthotopic lung cancer preclinical models." (PMID 37951973, 2023). "Targeted therapy against KRASG12C inhibits CD47 signaling and restores innate immune surveillance in animal models of lung cancer." (PMID 36413402, 2023). "Taken together, this study demonstrates that active KRAS can promote innate immune evasion of lung cancer through upregulation of CD47." (PMID 36413402, 2023). "Previously, smoking was found to be correlated with increased levels of PDL-1 in lung cancer and CD47 in brain metastases of lung cancer patients." (PMID 37566079, 2023). "Ye and colleagues first described induction of CD47 by IFNγ in lung cancer cells through a JAK–STAT1–IRF1 signaling pathway." (PMID 37958404, 2023). "Lung cancers exploit this “don’t eat me” signal by upregulating CD47 to evade the immune system, making it a promising therapeutic target." (PMID 37958404, 2023). "Given its prognostic relevance, its role in facilitating immune escape, and the number of agents currently in clinical development, CD47 blockade represents a promising next-generation immunotherapy for lung cancer." (PMID 37958404, 2023). "We further analyzed CD47 expression and localization in the cultured A549, H1299 lung carcinoma cells, and HBE normal human bronchial epithelial cells." (PMID 36823443, 2023). "SPC-A-1, A549, and 95D are human lung cancer cell lines with differences in aggressiveness, metastasis, drug resistance, and CD47 expression levels." (PMID 35646646, 2022). "al., reported that macrophage were able to kill CD47-expressing lung cancer when opsonized with anti-integrin b-3 antibody through ADCC mechanism instead of ADCP." (PMID 36077152, 2022). "We used 95D, SPC-A-1, and A549 human lung cancer cell lines, each of which express different concentrations of cell surface CD47 antigens, to evaluate the cytotoxic effect of 7DC2-VCMMAE and 7DC4-VCMMAE in vitro, measured as the relative viability rate." (PMID 35646646, 2022). "In other words, the expression of CD47 on the cell membrane of three lung cancer cells is in the order of 95D > SPC-A-1 > A549." (PMID 35646646, 2022).